MMP9 (matrix metallopeptidase 9)
Diseases named in the same sentence as MMP9 in open-access papers (continued):
Sharing a sentence is not in itself a finding about the gene and the disease.
pulmonary fibrosis (continued). "We also examined the levels of several other classical cytokines (including IFN-γ, IL-4, IL-12, IL-13) and several matrixmetalloproteinases (such as MMP2, MMP9) in this model of lung fibrosis." (PMID 26627341, 2015). "While many MMPs are purportedly involved in pulmonary fibrosis, MMP-9 is one of the most relevant pro-fibrotic members of the family." (PMID 25945502, 2015). "Our result suggests that 17(R)‐RvD1 administered during the fibrotic stage ameliorates pulmonary fibrosis through restoring MMP‐9 mRNA dramatically." (PMID 26660549, 2015). "For example, Rac1/ERK mediation of matrix metalloproteinase-9 (MMP-9) expression in alveolar macrophages is involved in pulmonary fibrosis." (PMID 25121739, 2014). "It has been found that MMP9 levels are elevated in patients with pulmonary fibrosis and furthermore, ablation of the MMP9 gene reduces IL-13-dependent lung remodelling." (PMID 22205929, 2011). "It is, however, possible that this neutrophil influx and the large amounts of MMP-9 it releases have a protective effect against the development of pulmonary fibrosis." (PMID 15663794, 2005). "The expression of MMP-9 has been reported to be elevated in the culture medium of alveolar macrophages from patients with idiopathic pulmonary fibrosis or bronchial asthma." (PMID 15642145, 2005). "MMP9 expressed by alveolar macrophages contributes to the remodeling of the pulmonary basement membrane, basement membrane stripping, and structural remodeling within the interstitium and alveoli, thereby promoting the development of pulmonary fibrosis." (PMID 40149666, 2025). "However, enhanced MMP9 activity is more commonly observed in the pathological state of pulmonary fibrosis, as elevated MMP9 expression levels have been detected in both bleomycin-induced mouse models and IPF patients." (PMID 40630478, 2025). "We hypothesized that proteins previously shown to be elevated in patients with pulmonary fibrosis (Amphiregulin, MMP-9, MMP-7, P-selectin, S100A12, and CXCL12) would be elevated in patients who develop fibroproliferative ARDS." (PMID 39106254, 2024). "In addition, TGF-β1 was proven to be an important regulator of MMP-3 and MMP-9 expression in the pulmonary tissues, which efficiently participate in the pathogenesis of lung fibrosis induced by chemotherapeutic agents." (PMID 38138222, 2023). "Further, andecaliximab, a monoclonal antibody against MMP-9, was developed at Gilead, which selectively binds to the allosteric site of MMP-9, reducing fibrosis in patients with idiopathic pulmonary fibrosis, particularly in patients with elevated levels of IFN-gamma." (PMID 36830719, 2023). "MMP-2 and MMP-9 have been attributed rather discordant roles in lung fibrosis." (PMID 35804363, 2022). "For example, it was found that the injection of miR-326 into mice with bleomycin-induced pulmonary fibrosis caused significant downregulation of TGF-β1, Smad3, matrix metalloproteinase-9 (MMP-9), and upregulation of Smad7, which in turn have good anti-fibrosis effects." (PMID 35147920, 2022). "LCN2 and MMP-9 have been reported to participate in pulmonary fibrosis development." (PMID 34991559, 2022). "HFD administration leads to pulmonary fibrosis by causing insulin resistance, a chronic inflammatory response, pro-oxidative/antioxidative imbalance, and increased levels of profibrogenic factors, including TGF-β, IL-17, NE, and MMP-9." (PMID 35115954, 2021). "Thus, AE protected against pulmonary fibrosis by repressing the expression of NE, MMP-9, TGF-β, and IL-17." (PMID 35115954, 2021). "The emerging data suggest that MMP-9 may be an early indicator of and candidate therapeutic target in respiratory failure and lung fibrosis in COVID-19 patients." (PMID 33800947, 2021). "Therefore, GMSC intervention alleviated bleomycin-induced pulmonary fibrosis by suppressing the expression of MMP-9 and NE." (PMID 35008524, 2021).
pulmonary fibrosis (continued). "Nevertheless, the punctual effect of C. pneumoniae on MMP-9 production in bronchial epithelial cells and alveolar macrophages remains unclear and further studies are needed to define the role of C. pneumoniae in MMP-9 secretion and lung fibrosis." (PMID 32054098, 2020). "Earlier studies have shown that the reduction in MMP-9/TIMP-1 ratio is important in promoting bleomycin-induced pulmonary fibrosis, which is well-supported by the results of present study showing decrease in MMP-9/TIMP-1 ratio during bleomycin-induced pulmonary fibrosis." (PMID 32440328, 2020). "As described in previously study, MMP2 and MMP9 secreted by macrophages and neutrophils in bleomycin-induced pulmonary fibrosis in early phase may play an important role in degrading the basement membrane, thereby facilitating the inflammatory cell migration." (PMID 28977826, 2017). "By contrast, transgenic overexpression of human MMP9 in macrophages attenuates lung fibrosis." (PMID 26944412, 2016). "However, administration of RPE significantly suppressed PQ-induced miR-21 expression, blocked FSTL1 expression, decreased p-p38MAPK, NF-kB65, p-Smad2/3 and MMP-9 protein levels and attenuated pulmonary fibrosis." (PMID 26758514, 2016). "Moreover, MMP-9 can activate latent TGF-β, a pleiotropic growth factor that directly induces a variety of responses associated with lung fibrosis and airway remodeling." (PMID 24822215, 2014). "Data from this study suggest that MMP-9 may play a role in these processes in coal mine workers and is consistent with the proposition that MMP-9 participates in the development of airway inflammation and pulmonary fibrosis in these miners." (PMID 21943057, 2011). "Gelatinase A (MMP-2) and gelatinase B (MMP-9) are two MMPs that appear to be involved in pulmonary fibrosis, but their specific roles in the process remain unclear." (PMID 15663794, 2005). "This suggests that PFD may mitigate silicosis progression through modulation of TLR2-mediated NF-κB p50/p65 pathway activation, consequently reducing TNF and MMP9 production-two critical mediators of inflammatory response and extracellular matrix remodeling in pulmonary fibrosis." (PMID 40470053, 2025). "They reported significant improvements in lung function, reduced collagen deposition, and increased MMP-9 expression in the high-dose group, whereas the low-dose group exhibited only modest effects, highlighting the benefits of higher doses for established pulmonary fibrosis." (PMID 41155309, 2025). "Iguratimod can inhibit the expression of TNF-α, IL-1, IL-6 and MMP-9 to reduce bleomycin-induced alveolar inflammation and pulmonary fibrosis in mice, suggesting that iguratimod may become an effective strategy for the treatment of pulmonary fibrosis." (PMID 37809072, 2023). "AE improves HFD-induced pulmonary fibrosis by counteracting obesity-associated insulin resistance, chronic inflammatory responses, and pro-oxidative/antioxidative imbalance and shows an antifibrogenic effect by suppressing TGF-β, IL-17, NE, and MMP-9 production in obese mice." (PMID 35115954, 2021). "As MMP9 primarily promotes pulmonary fibrosis linked to airway inflammation, it may well be that MMP9 may not be a critical mediator of AHR wherein the process is independent of airway inflammation." (PMID 35387021, 2021). "Accordingly, it is proposed that NAC may inhibit bleomycin-induced development of pulmonary fibrosis by increasing the MMP-9/TIMP-1 and MMP-9/TIMP-3 ratios, which eventually increases the degradation of collagen in the lungs to prevent its excessive deposition in the form of fibrosis." (PMID 32440328, 2020). "Our study showed that HPS2-mice had elevated transcript levels of MMP2 and MMP9, while broad upregulation of MMP2, -3, -8, -9, -12, and -14 transcripts was evidenced in the HPS1-mice, suggesting that the pathogenesis of pulmonary fibrosis might differ in the different HPS mutations." (PMID 32485920, 2020).
pulmonary fibrosis (continued). "In human lung fibrosis, MMP-9 expression could be inhibited with steroids and immunosuppressants." (PMID 27938355, 2016). "Therefore, in addition to downregulating miR-21 and Fstl l expression, puerarin might interrupt the TGF-β autocrine pathway by inhibiting MMP-9 activity and, thereby, suppress PQ-induced pulmonary fibrosis." (PMID 26758514, 2016). "This suggests that the MMP9, IL-6, and TNF-α collectively exert multiple effects in driving lung fibrosis progression." (PMID 40630478, 2025). "In this study, EPM administration suppressed fibrosis-related markers, including TGF-β1, p-Smad3, Collagen III, α-SMA, and MMP-9, while upregulating antifibrotic mediators such as TIMP-1, thereby reducing the MMP-9/TIMP-1 ratio and mitigating lung fibrosis." (PMID 40507891, 2025). "When stimulated by inflammation, macrophages secrete MMP2 and MMP9 to promote degradation of the surrounding matrix, thereby expanding the inflammatory response, which may be one of the reasons why the expression of MMPs is positively correlated with pulmonary fibrosis." (PMID 40181990, 2025). "The results of this study showed that MMP9 and TIMP1 expression were upregulated in the lung tissues of rats with BLM-induced pulmonary fibrosis." (PMID 40438789, 2025). "It has been revealed that there is a strong relationship between the extent of the fibrosis and the MMP‐9 levels, indicating that MMP‐9 plays a crucial role in the pathogenesis of pulmonary fibrosis." (PMID 38229198, 2024). "JTE-013 also inhibited the expression of fibrosis markers α-SMA, MMP-9, and COL1A1, and alleviated the symptoms of pulmonary fibrosis." (PMID 37895915, 2023). "The authors stated that the imbalance between MMP-9 and TIMP-1 can determine ARDS development and the tendency to pulmonary fibrosis." (PMID 37545954, 2023). "MMP9 was also an essential player in IL-13 mediating TGF-β1 secretion and was involved in pulmonary fibrosis and degradation of extracellular matrix." (PMID 35912246, 2022). "MMP-9 has been found to be involved in the process of pulmonary fibrosis, and TIMP-1 is a specific inhibitor of MMP-9." (PMID 35402615, 2022). "AdTGF-β1 was applied via orotracheal routes to the lungs of WT, MMP-2 KO, MMP-9 KO and MMP-2/-9 dKO mice on day 0 to induce lung fibrosis." (PMID 35804363, 2022). "The CytoHubba plug-in was then used to filter the top 10 nodes of the hub genes such as MMP-9 and TIMP-1, which are the common genes involved in pulmonary fibrosis." (PMID 35402615, 2022). "The results showed that levels of fibrosis markers (fibronectin (FN), matrix metalloproteinase 9 (MMP9), MMP2, connective tissue growth factor (CTGF), and Collagen I) significantly increased in bleomycin-induced lung fibrosis." (PMID 35039472, 2022). "As expected, the protein expression levels of FN, MMP9/2, CTGF, and Collagen I also decreased by Dot1l shRNA in lung fibrosis process." (PMID 35039472, 2022). "This evidence showed that BM-MSCs administration alleviated pulmonary fibrosis via impairing LPS-induced TGF-β and MMP-9 release." (PMID 34508136, 2021). "Then, additional fibrotic factors, such as collagen I, TIMP, and MMP-9, were analyzed to evaluate the inhibitory effect of DPSCs-HGF on lung fibrosis progression." (PMID 33747095, 2021). "AE improved HFD-induced pulmonary fibrosis by suppressing IL-17, TGF-β, NE, and MMP-9 expression and activating IL-10 and sirt-1 expression." (PMID 35115954, 2021). "A recent study showed that lncRNAPCAT29 inhibits pulmonary fibrosis via downregulating RASAL1/ERK1/2 signal pathway, which suppresses the expression levels of MMP2 and MMP9 in alveolar epithelial cells and pulmonary fibroblast cell differentiation." (PMID 33791201, 2021). "In this study, we aim to investigate the in vivo and in vitro roles of GSK-3 inhibition in the modulation of MMP-9 and MMP-2 and of their inhibitors TIMP-1 and TIMP-2 in the development of lung fibrosis." (PMID 34235177, 2021).
pulmonary fibrosis (continued). "Further, MMP9 gene expression was found raised with elevated protein in IPF and experimental lung fibrosis." (PMID 33672678, 2021). "Our analysis showed that eight genes (CSF2, CSF3, CXCL2, CXCL8, IL1B, IL6, MMP9, and TNF) are significantly overlapping with the lung fibrosis pathway with p-value 9.35e-11." (PMID 33362771, 2020). "PQ induced significant pulmonary fibrosis, as demonstrated by the elevated concentrations of VEGF, TGF-β1, and MMP-9 in the bronchoalveolar lavage fluids." (PMID 30744607, 2019). "In our study, ligustrazin treatment inhibited the expression of TGF-βl and MMP-9, suppressed total collagen, Collagen I and III, and attenuated PQ-induced pulmonary fibrosis." (PMID 30744607, 2019). "Macrophages secrete MMPs, including MMP9 and MMP12, which participate in the pathogenesis of pulmonary fibrosis." (PMID 30250465, 2018). "Alveolar macrophages are important producers of MMPs, including MMP9 and MMP12, which are vital players in pulmonary fibrosis." (PMID 30250465, 2018). "Through its regulation on MMP-9, R1R2 inhibits pulmonary fibrosis by abolishing fibrocyte infiltration across the subendothelial BM into the parenchyma of the lungs and decreasing fibrocyte differentiation into myofibroblasts." (PMID 28968441, 2017). "In the present study, we demonstrated that TSA prevented EMT and increases in MMP-9 and PAI-1, collagen 1a1, total collagen, and lung fibrosis parameters through the inhibition of HDAC4 activation in vivo." (PMID 28234968, 2017). "To assess effects of RPE in PQ-induced lung fibrosis, we measured miR-21 and FSTL1 gene expression with real-time PCR and p-p38MAPK, NF-kB65, p-Smad2/3 and MMP-9 protein expression with western blotting in lung tissue from mice on day 14 after PQ challenge." (PMID 26758514, 2016). "Our findings suggest that blockade of the Wnt/β-catenin signaling pathway by silencing β-catenin prevents the development of silica-induced lung fibrosis, which is related to the expression of MMP2 and MMP9, and secretion of TGF-β1 in the lung." (PMID 26340635, 2015). "If MMP‐9 is decreased and TIMP‐1 is increased in lung tissue, it promotes ECM accumulation leading to pulmonary fibrosis." (PMID 26660549, 2015). "Previous studies have reported that DBT can reduce bleomycin-induced pulmonary fibrosis in rats by boosting matrix metalloproteinases, MMP-1, MMP-9, and TIMP-1 expression." (PMID 25861366, 2015). "APN treatment significantly decreased the lung fibrosis scores, protein and mRNA expression of pulmonary TGF-β1, CTGF and α-SMA content, and blood MMP-9 and TIMP-1 in a dose-dependent manner (p<0.05)." (PMID 25945502, 2015). "Doxycycline is a potent MMP inhibitor which is able to reduce MMP-2 and MMP-9 mRNA expression and MMP-2 production in vitro and thereby attenuates collagen accumulation in pulmonary fibrosis." (PMID 24675764, 2014). "Such increases explain perhaps the trend toward significance of theinverse correlation of MMP-9 levels with DLCO and TLC measurements, since themajority of our patients with pulmonary fibrosis had diffuse SSc." (PMID 19190762, 2008). "In the early silicosis stages, MMP9 disrupts lung tissue and increases the infiltration of inflammatory cells and corresponding inflammatory mediators, such as TNF-α and other cytokines, to promote the development of pulmonary fibrosis." (PMID 40470053, 2025). "Early inhibition of MMP9 and TIMP1 in lung tissue and maintenance of balance between alveolar collagen synthesis and degradation are expected to become new strategies for the treatment of pulmonary fibrosis." (PMID 40438789, 2025). "Elevated levels of MMP-7, MMP-9, and MMP-13 in severe COVID-19 cases are indicative of ongoing tissue remodeling and inflammation, which could contribute to lung fibrosis and other long-term complications." (PMID 40557167, 2025). "Notably, the AMPKα/MMP9 axis attenuates skeletal muscle fibrosis, while PPAR-γ/NLRP3/NF-κB signaling mitigates pulmonary fibrosis progression." (PMID 40969268, 2025).
pulmonary fibrosis (continued). "MMP-9 overexpression can degrade all components of the extracellular matrix and nonmatrix proteins, thereby prompting pulmonary fibrosis." (PMID 38913698, 2024). "In the present study, the expression levels of COX-2 i-NOS, MMP-9, EPO-R, and Cyt-C, examined using immunohistochemical methods, were chosen to assess the inflammatory and fibrotic processes in the experimental model of lung fibrosis." (PMID 39338226, 2024). "Additionally, the study found that Tan reduced the expression of Collagen I, MMP9, and TGF-β1 in BLM-treated mice, which are all indicators of pulmonary fibrosis." (PMID 37781713, 2023). "Furthermore, ELISA was used to detect pulmonary fibrosis markers COL-1, COL-3, WNT, Vimentin, β-Catenin, Fibronectin, α-SMA, N-Cadherin, E-Cadherin, TWIST, CTGF, FGF2, PDGF-α, MMP2, MMP8, MMP9, MMP13, TIMP1, TGF-β, Smad2, and Smad3 expression levels." (PMID 37812357, 2023). "Therefore, in the current study, we have examined the role of single MMP-2 or MMP-9 deletion and of combined MMP-2/-9 double deletion in a well-defined murine model of lung fibrosis induced by adenoviral exposure to biologically active TGF-β1." (PMID 35804363, 2022). "Knockdown or pharmacological inhibition of DOT1L could block TGF-β1-induced upregulation in the protein levels of lung fibrosis markers, such as CTGF, FN, and MMP9." (PMID 35039472, 2022). "In addition, YJT not only decreased airway wall thickness, average alveolar intercept, and lung fibrosis, but it also suppressed the expression of matrix metallopeptidase (MMP)-7, MMP-9, and transforming growth factor-B (TGF-β) and collagen deposition." (PMID 35035511, 2022). "In this sense, the present study evaluated the histopathological features and immunohistochemical biomarkers (ACE-2, AKT-1, Caveolin-1, CD44v6, IL-4, MMP-9, α-SMA, Sphingosine-1, and TGF-β1 tissue expression) involved in the TGF-β1 signaling pathways and pulmonary fibrosis." (PMID 35008594, 2021). "Also, knocking out P2X7R inhibits pulmonary fibrosis, and P2X7R levels contributes to the release of MMP9, an important mediator of myocardial remodeling." (PMID 31681001, 2019). "We speculate that inhibition of MMP9 and MMP12 induced by blocking 4-1BB signaling attenuates CS-induced pulmonary fibrosis via lessening the maturity of TGF-β and the deposition of collagen type I. Future studies are needed to address this hypothesis." (PMID 30250465, 2018). "Acute inflammation is followed by EMT, collagen deposition, and lung fibrosis through the production of profibrotic cytokines, including transforming growth factor (TGF)-β, plasminogen activator inhibitor (PAI)-1, and matrix metalloproteinase (MMP)-9." (PMID 28234968, 2017). "MMP‐9 and TIMP‐1 play an important role in the development of pulmonary fibrosis." (PMID 26660549, 2015). "Interestingly, TGF-β induced lung fibrosis in mice was primarily due to TIMP up-regulation, and a recent study demonstrated that over-expression of MMP-9 by alveolar macrophages in mice attenuated the fibrotic reaction after bleomycin instillation." (PMID 25496490, 2014). "Indeed, levels of MMP-2 and MMP-9 protein and MMP7 mRNA are elevated in the lungs of patients with human idiopathic pulmonary fibrosis (IPF) and MMP-13 expression is increased in the lungs of patients with chronic obstructive pulmonary disease (COPD)." (PMID 23593124, 2013). "MMP-9 is a major MMP and is known to be involved in lung fibrosis." (PMID 22016783, 2011). "However, MMP-9 activity to regulate the lung fibrosis response is cell-specific; MMP-9 did not affect the lung fibrosis response in transgenic mice overexpressing profibrotic interleukin (IL)-13 in airway club cells." (PMID 36834561, 2023). "It was thought that the MMP-9/TIMP-1 ratio could indicate whether pulmonary fibrosis would be involved in ARDS or not." (PMID 37545954, 2023).